IL6 (interleukin 6)
Diseases named in the same sentence as IL6 in open-access papers (continued):
Sharing a sentence is not in itself a finding about the gene and the disease.
infection (continued). "The correlation analysis revealed a significant correlation between LBP and CRP at 6 h (P <0.001), 12 h (P = 0.003) and 3 d (P <0.001), IL-10 and IL-6 at 7 d (P <0.001), and IL-6 and CRP at 7 d (P = 0.001) in patients with infection." (PMID 25613713, 2015). "Absolute number (×104) ofIL-12 and IL-6 producing dermal CD11c+ DCs andF4/80+ macrophages in C57BL/6 and BALB/cmice at 48 h post infection with L.major alone or in combination with 50μg Pam3CSK4." (PMID 25738770, 2015). "The results showed that MJWQH significantly increased the survival rate of H1N1-infected mice and suppressed the production of TNF-α, IL-1, IL-6, MCP-1, RANTES, and IFN-α on day 4 after infection." (PMID 26089947, 2015). "In contrast, when the cells were pretreated with EM900 before infection and treated with EM900 after infection, the infection-induced secretion of IL-6 at 72 h after infection was reduced compared with vehicle-treated cells." (PMID 26462747, 2015). "As expected infection of bone marrow derived macrophage (BMDM) cells from C57/BL6 mice with MCMV triggered expression of the host pro-inflammatory cytokines IFNβ, IL6 and TNF." (PMID 25856589, 2015). "It is has been reported that IL-6 levels are suppressed during active infection in human fibroblasts via transcriptional activation in part by HCMV IE2 protein and posttranscriptional destabilization of IL-6 mRNA." (PMID 25573478, 2015). "Proteins that are routinely used to support diagnosis of infection include procalcitonin, C-reactive protein (CRP), and Interleukin-6 (IL-6)." (PMID 25785720, 2015). "Primary wt AMs exposed ex vivo to RSV at different multiplicities of infection (MOI) produced IFN-α, IL-6 and TNF-α." (PMID 26688048, 2015). "A significant increase of IL-6 and TNF-α were also observed at 4 or 8 h following infection with D39 or TIGR4." (PMID 26683708, 2015). "In contrast, at day 14 after infection, increased levels of the pro-inflammatory cytokines TNF-γ, IFN-γ, IL-2, IL-6, and IL-17 were observed in mice that had received a high inoculum dose relative to mice that had received medium and low doses." (PMID 25889515, 2015). "Infection of M2 macrophages with C. pneumoniae resulted in significantly enhanced release of TNF-α, IL-6, IL12p70, IL-12p40, IL-10, CCL17, and CCL24 as compared to uninfected M2 cells." (PMID 26606059, 2015). "Peritoneal infection by Enterococcus faecium is sensed predominantly by macrophages via TLR2 which then secrete IL6, TNF-α, MIP-2, and KC during early infection." (PMID 26172831, 2015). "The rapid induction of IL-6, MCP-1, IL-15 and MIP-1α in serum at day 1 after infection suggests an immediate activation of the macrophage/monocyte/dendritic cell innate immune system." (PMID 25946071, 2015). "In parallel with decreased lung monocyte infiltration, SSa treatment attenuated PR8-induced IL-6 production in the lungs at all time points studied and attenuated TNF-α production from days 2 and 4 following PR8 infection." (PMID 26637810, 2015). "The inflammatory markers IL-6, IL-1α and IL1-β were expressed at similar levels in both infections at early times, while TNFα was preferentially present in S. mitis infections." (PMID 26171605, 2015). "Instead, we found that the SaeRS TCS plays a significant role in the production of not only IFN-γ but also IL-1β, IL-6, MIP-2, and IL-17A/F during murine infection." (PMID 26147796, 2015). "And also, we confirmed the secretion of IL-6 and IFN-β from KIOM-C-treated RAW264.7 cells in the presence of PR8-GFP infection." (PMID 25942440, 2015). "Significant up-regulation of proinflammatory cytokines such as IL1B, IL6, and IL8 was observed, correlating with protein levels, infection status and histopathological findings." (PMID 26018580, 2015). "A subsequent study demonstrated a requirement for IL-6 in the eradication of lymphocytic choriomeningitis virus (LCMV) due to a late spike in IL-6 production, 25 days post infection." (PMID 25615546, 2015).
infection (continued). "In the SS2 infection, IL17D was elevated by 2.07-fold, which can stimulate production of IL6, IL8, and GM-CSF production in endothelial cells." (PMID 25906258, 2015). "Overall, IAV infection dampened the total number of neutrophils, MIP-2 and IL-6 levels, while it increased the total number of macrophages, lymphocytes and MCP-1 levels by day 9 post-infection." (PMID 25923474, 2015). "As expected, we observed a 2260- and 80-fold induction of IL-6 in the lungs and spleen, respectively, as well as a 21-fold induction of TNF in the lungs of the host at 24 hours post-infection." (PMID 26250699, 2015). "The cytokine profile (IL-10, IL-6, TNF-α) elicited upon infection with N. gonorrhoeae correlates well with the M2b-MФ phenotype." (PMID 26125939, 2015). "At later stages of infection, RRV-infected OA hOBs showed significantly increased IL-6, IL-1β and CCL2 expression compared to healthy infected controls." (PMID 25407789, 2014). "Specifically, at both days 3 and 6 post-infection, IFNG, IL6, TNF, MIP1B and IL10 were all significantly diminished in MYD88-deficient mice as compared to wild-type mice." (PMID 25192715, 2014). "In the combination therapy experiment, increased levels of IL-6 were detected in the sera of ICP1, ICP3, and ITP3, all of which were humanely euthanized or died after infection." (PMID 24945244, 2014). "The expression levels of interleukins (IL-6 and IL-8), chemokines (MCP-1, MIF and GROα) and growth factors (G-CSF and GM-CSF) increased steadily from 8 h until 24 h post infection whereas the parasite burden decreased erratically until 24 h post infection." (PMID 24886982, 2014). "The other investigated pro-inflammatory cytokines were low (IL-6 on day 3 and IL-1β and IL-6 on day 7) or undetectable (IL-1β and IL-12p40 on day 3) during MOI 1 infection." (PMID 25386849, 2014). "IL-10 was increased around week 5 post infection, while the stress cytokines IL-6 and MIP-1α were significantly increased late in infection." (PMID 25398130, 2014). "In contrast, infection with ECTV and ECTV-Δ005 prevented transcriptional upregulation of TNFα, IL-1β, and IL-6." (PMID 25122471, 2014). "In the present study, we examined the levels of TNF, IL-1β, IL-6, IL-8, and CCL5 in the supernatants of HTNV-infected HUVECs at 48 h post infection using ELISA." (PMID 24714064, 2014). "Analysis of the correlation between sCD14, IL-6, PCT, and the infection markers revealed a significant correlation only between the IL-6 concentration and the ESR level (r=0.497, p=0.008)." (PMID 24948983, 2014). "We analyzed the concentrations of the cytokines IL-12p70, IL-12p40, IL-10, IL-6 and TNF-α in supernatants of BMDC 48 hours after infection with L. major promastigotes, or stimulation with LmAg." (PMID 25255101, 2014). "Similar differences between Ity and Ity3 were observed for IL-6, IFN-γ and IL-12 at day 5 post-infection with Ity3 presenting significant lower levels of these three cytokines when compared to Ity." (PMID 24505352, 2014). "At 8 h post infection with PRU, IL-6, IL-8, MIF, MCP-1 synthesis and parasite levels peaked, when GROα and Rantes synthesis remained low." (PMID 24886982, 2014). "After 5 days of infection, however, plasma levels TNF-α, monocyte chemo attractive protein (MCP)-1, IL-6, IL-10 and IL-12 were markedly elevated in all WT mice." (PMID 25115174, 2014). "In contrast to TS mice, the low level of pleiotropic cytokines like IL-6 (seen here) and regulatory cytokines like IL-10 in TR mice may be pointed as a mechanism responsible for these lesions and render them unable to counteract the inflammatory effect induced by the infection." (PMID 25437299, 2014). "Serum proinflammatory cytokines were similar in both age groups, whereas significantly lower levels of IL-1beta, IL-18, IL-6, IL-12 and IL-15 were detected in the lungs of SARS-CoV-infected aged monkeys at either 5 or 10 days post infection." (PMID 24642138, 2014).
infection (continued). "In human monocytes, the focus of this study, we have previously shown that infection with F. tularensis, leads to diminished responses of cytokines such as TNF-α, IL-6, IL-8, and IL-12 among others." (PMID 24783062, 2014). "Challenge with the respiratory pathogen induced an early increase (12 hours post-infection) of TNF-α, IL-1β and IL-6 levels and a late increase of IFN-γ (48 hours post-infection) in BAL and serum, in both experimental groups." (PMID 24691464, 2014). "In parallel with reduced survival rates in Siglec-E KO animals, serum levels of IL-6 and acute phase protein, serum amyloid A (SAA) 18 h after infection were substantially higher in Siglec-E KO animals relative to WT controls." (PMID 24391502, 2014). "The il6 gene was identified during the GSEA analysis, and IL6 is produced by HIBCPP cells after infection with Nm, most pronounced by MC58siaD−." (PMID 25347003, 2014). "After infection, the expression levels of TNF-α and IL-6 in the colon were two-fold higher in PPARγVillinCre+ mice compared to PPARγVillinCre- mice." (PMID 24465207, 2014). "Fifth, expression of pro-inflammatory cytokines such as IL-6 and IFN-γ was more than 50% lower in ex vivo biopsies derived from colon and MLNs upon infection with the mutant versus the parental strain." (PMID 24587249, 2014). "Herein, our findings clearly indicate that compounds 1 and 2 have been able to inhibit the secretion of IL-6 and IFN-γ induced by HSV-1 KOS wt infection of Neuro-2a cells." (PMID 25147828, 2014). "For the inflammatory response, nicotine treated mice had significantly less production of IL-6 on day 3, MCP-1 and RANTES on day 7 after pdmH1N1 infection compared with control mice." (PMID 24465940, 2014). "By 24 h of infection, however, expression of all four anti-viral genes and IFN-β and IL-6 was clearly up-regulated (p<0.05) in all three cell types; BEAS-2B cells displayed the highest expression of IRF-7, STING, Mx1 and IL-6." (PMID 25313647, 2014). "qRT-PCR test showed that after 4 hours of ST169 (H1N1) infection, compared with the 4 hours control, AM expressed dramatically higher levels of M1 markers, including TNF-α, MCP-1, iNOS, IL6 and IL-12." (PMID 25105760, 2014). "Macrophages have been reported to be the major source of interferon α/β, which plays a key role in viral clearance, and are important sources of IL-1β, IL-6 and TNF-α, which are responsible for the acute phase response to the infection." (PMID 25232724, 2014). "Gp120 is shed from the mature virion in vitro, has been detected in the plasma of patients early during the infection and correlated with higher levels of TNF-α, IL-6, IL-10, INF-α, and IFN-γ." (PMID 25309527, 2014). "Paired samples of Bronchiolo-alveolar lavage fluid (BALF) and blood from each subject were analysed for putative biomarkers of infection: Cellular (TREM-1, CD11b and CD62L) and soluble (IL-1β, IL-6, IL-8, sTREM-1, Procalcitonin)." (PMID 25289689, 2014). "Cytokines including IL-6, GRO-γ and RANTES are up-regulated in response to S. aureus clinical isolates in epithelial cell infection models." (PMID 25398383, 2014). "We constantly observed that in AGS cells infected with H. pylori in the presence of IL-6, STAT3 phosphorylation reappeared at 120 min after it declined to almost undetectable levels at 60 min after infection." (PMID 24824519, 2014). "TNF, IL-6, MIP-2, KC and MCP-1 were all highly expressed in response to infection in Camp −/− mice at 6 hours, and resolving by 24 hours, but were not significantly different from the responses quantified in infected wild type mice." (PMID 24887410, 2014). "The mRNA and protein expression of TNF-α and IL-6 were increased significantly in BMDM after Mmass R morphotype infection, compared with those with S morphotype infection." (PMID 24402617, 2014). "At euthanasia, spleen MC of the infection group had produced significantly less IFN-γ, TNF-α, IL-1β, IL-6, IL-8 and IL-12p40 than MC of the other groups." (PMID 25252649, 2014).
infection (continued). "Extracellular S100A9 contributes to production of pro-inflammatory mediators during infection as evident from reduced TNF and IL-6 levels in the lung of S100A9 antibody treated mice." (PMID 24391503, 2014). "While TLR3 ablation protected mice from WNV lethal infection by decreased systemic TNF-α and IL-6 production and BBB permeability, there is a report demonstrating that TLR3 molecules are essential in protecting from WNV infection." (PMID 25188232, 2014). "A prospective study was carried out in 61 patients with S. aureus bloodstream infection and circulating levels of IL-6, GRO-γ, RANTES and leptin were assessed over the course of the infection." (PMID 25398383, 2014). "IAV infection significantly increased the levels of all tested proinflammatory cytokines (IL-1β, IL-6, IL-2, TNF-α, IFN-α, IFN-β and IFN-γ) in lung homogenates between 1.2- and 13.7-fold relative to the baseline (before infection)." (PMID 24865588, 2014). "CK1 induced high pulmonary levels of proinflammatory cytokine IL-1β, IL-6 and chemokine RANTES at all studied time points after infection." (PMID 25232731, 2014). "Treatment of mice with either AMP or AZM alone or in combination after infection was able to significantly down regulate the serum TNF- α, IFN- γ and IL-6 levels at 2, 3, 4, 5 and 6 hours post antibiotic treatment." (PMID 24565171, 2014). "According to their reports, PCT indicates infection more reliably than traditional indicators such as body temperature, WBC, CRP, or cytokines (IL-6, IL-8)." (PMID 25960877, 2014). "In agreement with a function of the IκBζ pathway during infection of HIBCPP cells with Nm, IκBζ target genes were induced on RNA (il6) as well as on protein level (il6, g-csf, gm-csf)." (PMID 25347003, 2014). "Here, in vitro infection showed that both isolates induced a strong production of NO and the cytokines TNF-α, IL-6, IL-1α, IL-1β, and IL-10." (PMID 24886263, 2014). "Similar to this study, we observed significant up-regulation chemokines and cytokines, such as CCL3, CXCL10, IL1RN, IL6 and TNF, throughout infection." (PMID 25079789, 2014). "Homogenates of kidneys from CD11cΔSyk mice showed higher levels of IL-6, KC, MIP-1α, IL-1β, TNF, IL-1α and MCP-3 at days 1 or 2 post-infection when compared to control mice." (PMID 25033445, 2014). "Our results indicate that IL-6, IL-8, and MCP-1 were much more potent than IL-10 in promoting death due to a secondary infection." (PMID 24886652, 2014). "At early stages of infection the permeability of lung vasculature is increased due to enhanced release of proinflammatory cytokines (TNF-α, IFN-γ and IL-6)." (PMID 24565171, 2014). "Only background levels of IL-6 and TNF-α were seen with infections by the LRV-negative Lae 372 parasites, as it was observed with the Lg M4147 LRV1-negative control clone and non-infected macrophages." (PMID 24762979, 2014). "Although RRV-induced IL-6, TNF-α and CCL2 were lower in the OA hOBs compared to infected controls during early infection, the expression of these osteotropic factors in OA hOBs, with the exception of TNF-α, was significantly elevated at 96 hpi." (PMID 25407789, 2014). "On other hand, monocyte and neutrophil recruitment, through KCs derived IL-6, IL-12, IL-1β, TNF-α, NO and chemokines (MIP-1α/β, MCP-1, MIP-2) limits the infection." (PMID 24976841, 2014). "At the time of infection, a bacterial component such as lipopolysaccharide or a cytokine such as tumor necrosis factor-α (TNF-α) or interleukin-6 (IL-6) induces high expression of the calcitonin-I gene, which activates the continuous release of PCT." (PMID 25960877, 2014). "Serological analyses showed elevated mean serum levels of IL-6, IL-1β, and CRP in the MRSA-infected animals during the early phases of infection." (PMID 25184249, 2014).
infection (continued). "Although the proportion of GATA-3+ Treg cells increases with infection in both strains, the proportion of GATA-3+ Treg cells and expression of GATA-3 within the MLNC Treg-cell population remains significantly lower in IL-6−/− mice." (PMID 24185641, 2014). "During infection, hepcidin is directly induced by LPS via TLR4 activation and during inflammation hepcidin is induced by IL-6." (PMID 25762501, 2014). "Infection increased secretion of cytokines/chemokines TNF-α, IL-6, TIMP-1, IL-1RA, G-CSF, TREM, KC, MIP-1α, MIP-1β, MCP-1, and MIP-2 in resident macrophages." (PMID 24416445, 2014). "Three cytokines (IL-6, IFN-γ, IL-10) increased significantly in the early stage of infection, but they all decreased to control levels at the late stage." (PMID 24666970, 2014). "Quantitative PCR data revealed that MRSA-infection predominantly induced expression of TLRs 1, 2, 6, NR4A2, and inflammatory cytokines IL-8, IL-6, TNFα in hMSCs." (PMID 24661536, 2014). "Gavage infection resulted in high levels of IFNγ, CCL2 and IL-6 already at day 2, followed by the gradual decrease of these cytokines." (PMID 25919005, 2014). "Serum IL-6, IL-10, and IFNγ continued to increase during the clinical course; IP-10 and MCP-1 remained at a high level from the beginning of infection." (PMID 25003343, 2014). "Although the levels of IL-6, IL-8, and MCP-1 in the MTSG and LTSG were significantly different in the early phase, the MTSG patients survived until the secondary infection." (PMID 24886652, 2014). "In regards to the mucosal inflammatory reactions, proinflammatory cytokines IL-1beta, IL-6, IL-15, IL-12 and IL-18 were all significantly lower in the lungs of SARS-CoV-infected aged animals at either day 5 or 10 post infection." (PMID 24642138, 2014). "The five clinical parameters, IG#, CRP, LBP, IL-6 and SOFA score were analyzed for their discriminative power to diagnose infection." (PMID 23398965, 2013). "On Day 1 and Day 3 post infection, bronchoalveolar lavage fluid (BALF) protein concentration and levels of cytokines including IL6, TNFα, IL1β, Interferon-γ and IL17 were measured." (PMID 23826353, 2013). "The anti-H5N1 effect was very likely due to the innate immune recognition of EAP and the secretion of innate immune mediators (IL-6, TNF-α and IFN-γ) before infection." (PMID 24159339, 2013). "Tulobuterol (0.1 μmol/L) reduced the baseline secretion of IL-1β, IL-6, and IL-8 for 24 h before RV14 infection compared with the levels observed in cells treated with vehicle (0.001% ethanol)." (PMID 24303127, 2013). "Rage−/− mice did demonstrate reduced TNFα, IL-6 and KC concentrations in BAL fluid 24 hours post infection." (PMID 24342460, 2013). "CSFV infected cells induced to express high levels of IFN-α, IFN-β, IL-1β, IL-6 and TNF-α in a dose-dependent way within 24 h post-infection (hpi)." (PMID 24034559, 2013). "In the presence of immune sera and upon infection, TRIM21 also activates a proinflammatory response, resulting in secretion of tumor necrosis factor alpha (TNF-α) and interleukin-6 (IL-6)." (PMID 23596308, 2013). "Remarkably, by day 14 PI GW9662 treated mice had sustained the stark increase in IL-6 while simultaneously expressing significantly elevated levels of colonic TGF-β and IL-17 further suggesting a Th17 effector response late during infection." (PMID 23469071, 2013). "When cardiomyocytes were pre-incubated with IL-10 (20 ng/ml), Q-RT-PCR results showed a significant decrease in IL-6 and TNF-α mRNA levels after 4 h of infection." (PMID 24260222, 2013). "And in vivo, strong secretion of IL-6, IL-8, and G-CSF or of IL-6, IL-8 and CCL-2, respectively, was observed following infection of cynomolgus macaques (Macaca fascicularis) with MPXV or CPXV, respectively." (PMID 23425254, 2013). "IL-6 is the stimulus to CRP production, and CRP is considered a good marker for infection in later stages." (PMID 23401697, 2013).